BRAF (B-Raf proto-oncogene, serine/threonine kinase)
Diseases named in the same sentence as BRAF in open-access papers (continued):
Sharing a sentence is not in itself a finding about the gene and the disease.
tumor (continued). "Tumor growth was substantially inhibited upon the short-term treatment with the BRAF and MEK inhibitor combination (On-tx group), and the tumors gradually progressed after 60 days of treatment (Resistance group), suggesting CR was successfully established in these cells." (PMID 34304249, 2021). "The BRAF gene in the tumor was also significantly silenced in vivo." (PMID 33546290, 2021). "KRAS, BRAF, and PIK3CA mutations are highly concordant between primary tumors and distant metastatic CRC tumors, indicating that either type of tumor tissue could be useful as a source to detect KRAS mutations for the selection of anti-EGFR therapy." (PMID 33652647, 2021). "Notably, this tumor had both APC and BRAF mutations, which are generally exclusive, identified in separate subclones based on their prevalence." (PMID 34488871, 2021). "CIMP-high CRCs are associated with distinct clinicopathological and molecular features such as older age, female preponderance, proximal tumor location, higher grade, reduced COX-2 expression, increased frequency of TGFBR2 mutations, and high rate of MSI, KRAS, and BRAF mutations." (PMID 33652647, 2021). "In addition to TERT promoter mutations, CM frequently harbors BRAF mutations, which are known to activate the downstream kinases MEK1/2 and ERK1/2, resulting in tumor proliferation." (PMID 34071371, 2021). "However, BRAF selective inhibitors are effective only in BRAF mutant tumor models and have paradoxically activated ERK signaling in KRAS mutant or RAS/RAF wild type tumor models." (PMID 34805167, 2021). "Taken together, the concordance rates of the tumor tissue versus plasma and the metastatic lymph node versus plasma of BRAF results were 23.9% (17/71) and 11.1% (3/27), respectively, which did not display any statistical association (κ = 0.032, p = 0.465; κ = 0.030, p = 0.561, respectively)." (PMID 33915745, 2021). "Activating mutations of BRAF lead to consecutive downstream activation of the RAS–MEK–MAPK signaling cascade, promoting cell proliferation, and survival while inhibiting apoptosis, and driving tumor growth." (PMID 35155453, 2021). "However, the genes such as KMT2D, DNAH11, and BRAF, which have a positive correlation with tumor immunity level, also up-regulated several immune-related miRNAs." (PMID 34211853, 2021). "Oncogenic mutation BRAFV600E is found in up to 50% of human melanomas; mutant BRAF protein induces internalization of pMHC-I complexes and their intracellular sequestration within endo-lysosomal compartments, facilitating tumor immune evasion via reduced surface pMHC-I display." (PMID 34201655, 2021). "Differences in tumor mutational profile, location, histology, and survival outcomes were compared in patients with EGFR- versus BRAF-mutated tumors, and microarray data from The Cancer Genome Atlas was used to assess differential gene expression between the groups." (PMID 34625582, 2021). "At present, BRAF status is assessed using a tumor biopsy, but ctDNA-based mBRAF detection could become a new standard being a less-invasive and faster strategy for accurate BRAF assessment (within days instead of weeks)." (PMID 34359813, 2021). "The proportion of BRAF activation may potentially increase in the context of tumor progressing on osimertinib in the adjuvant setting." (PMID 34575554, 2021). "Of note, it appears that upfront triple therapy (CDK4/6-BRAF-MEK-inhibitors) may have superior efficacy compared to the addition of CDK4/6 inhibitor after tumor acquisitions of BRAF/MEK inhibitors resistance." (PMID 34071228, 2021). "Patients with BRAF V600E mutation, over-expression of BANCR and down-regulation of miR-9 have been shown to need earlier surgical management particularly total thyroidectomy in primary surgery in order to decrease tumor recurrence." (PMID 34409032, 2021). "Moreover, recent studies have indicated that BRAFV600E detection through circulating tumor DNA prior to treatment is predictive of response to BRAF/MEK inhibitors." (PMID 34123788, 2021).
tumor (continued). "CSF1 inhibitors may further enhance the anti-tumor efficacy of BRAF inhibition in preclinical models and could also be considered." (PMID 34691054, 2021). "Patients with mCRC and BRAF-V600e-mt RAS-wt tumours may benefit from the addition of BRAF inhibitors to their adjuvant therapy." (PMID 34940086, 2021). "Of the 72 patient specimens with known MSI and BRAF status (MSS n = 30, MSI-H:BRAF mutant n = 19 and MSI-H:BRAF wild type n = 23), 19 patients from each subgroup were selected for analysis and of these 57 patients, 56 patient tumour specimens were analysed by CGE." (PMID 34198876, 2021). "In the evaluated cohort of PDLMM patients, including our case, only six tumor samples were analyzed for BRAF mutation, which were all negative." (PMID 33921303, 2021). "In tumor case 41, BRAF p.V600E and DNMT3A p.P904L mutations were both present at clonal allele frequencies of 32%, indicating their acquisition early during tumorigenesis and presence in the majority of tumor cells." (PMID 34661724, 2021). "Next, the Cox regression hazard model was performed using the following confounder variables: age, gender, tumor stage, type of tumor (primary/metastatic), and presence/absence of BRAF, NRAS, and NF1 mutations." (PMID 34502169, 2021). "EGFR/BRAF inhibition may render a tumour responsive to checkpoint blockade by temporarily converting an MSS tumour into an immunogenic MSI tumour and igniting a lymphocytic immune response." (PMID 34302062, 2021). "To date, the lack of tractable tumour models that faithfully recapitulate the topography and molecular landscapes of oncogenic BRAF-driven rCRCs has hampered efforts to decipher the underlying molecular mechanisms and develop targeted therapeutics." (PMID 34103493, 2021). "Overall, in our cohort of 6 metastatic CRC patients all harbouring KRAS mutations and none carrying BRAF mutations, 193 genes turned out to be significantly deregulated in the tumour compared to the paired stroma." (PMID 34439343, 2021). "Patients were well balanced across the two groups in terms of age, sex, body mass index (BMI), preoperative comorbidity, preoperative chemotherapy, presentation of PM, preoperative CEA level, preoperative CA19-9 level, histology, tumour grade, adjuvant chemotherapy, BRAF status, and MSI (P > 0.05)." (PMID 34446046, 2021). "In samples harboring BRAF V600E mutation, up-regulation of BANCR has been correlated with lymph node involvement, while in BRAF V600E negative samples, over-expression of this lncRNA has been linked with invasion of tumor to thyroid capsule." (PMID 34409032, 2021). "Patients with such tumours might benefit from BRAF inhibitors, at least in the setting of disease recurrence." (PMID 33293629, 2021). "Similarly, sequencing of BRAF and KIT mutations in malignant melanoma revealed a high degree of heterogeneity between CTCs and tumor tissue." (PMID 34412644, 2021). "Only 26.8% of tumours were assessed for BRAF mutation in this study as BRAF tests were not part of routine molecular profiling requests during the period when this study cohort received Lonsurf, between 2016 and 2017." (PMID 34207352, 2021). "Additionally, vemurafenib led to secretion of many other factors in tumor microenvironment and contribute to the microenvironment-driven resistance to BRAF inhibition due to the dense network in tumor stroma." (PMID 34371697, 2021). "An intrinsic (relative) resistance of tumor cells with mutant BRAF or KRAS to chemotherapy may contribute to the poor prognosis that is associated with the presence of these oncogenes." (PMID 34771595, 2021). "The observation that BRAF-mutant CRCs displayed six hyper-methylated genes with tumor suppressive functions respect to BRAF-negative CRCs may shed light on their possible re-expression following treatment with demethylating agents." (PMID 34277443, 2021).
tumor (continued). "Gain-of-function mutations of ubiquitin-specific protease (USP) 8, USP48, and BRAF genes may subsequently cause overexpression of epithelial growth factor receptor (EGFR), and enhance POMC transcription, cell proliferation, and tumor growth." (PMID 33986726, 2021). "Patients who have BRAF wild-type tumor are more likely to experience a complete response to DPCP." (PMID 32542563, 2021). "We found that 9 miRNA were related to tumor growth, 14 to tumor growth and invasiveness, 28 to invasiveness, and 66 to therapies resistance (62 to anti-BRAF treatment, 3 to chemotherapy and 1 to radiotherapy)." (PMID 34206867, 2021). "In MMbraf5, BRAFV600E mutation was identified in a primary tumor but not in a LN metastasis, suggesting heterogeneity of the BRAF genotype." (PMID 33731038, 2021). "The available tumor genotyping data showed mutation of KRAS for 16/43, mutation of NRAS for 3/29, NRAS unknown status for 14/43, mutation of BRAF for 5/35, and BRAF unknown status for 8/43." (PMID 33934494, 2021). "BRAF V600E IHC staining showed the variant BRAF protein was expressed exclusively in the cytoplasm of tumor cells but not in the adjacent healthy tissue." (PMID 34613404, 2021). "If the tumor had not possessed the BRAF V600E mutation, no other treatment strategies would have been available for the patient due to his age." (PMID 33215864, 2021). "Immunochemistry of tumor tissues of patients suggest that the expression levels of PD-1, PD-L1, CTLA-4, TIM-3, and LAG-3 are significantly higher in BRAF mutated samples than in BRAF wild-type samples." (PMID 34381786, 2021). "Mutations in ARID1A (p = 0.0205), ARID2 (p = 0.0207), BRAF (p = 0.023) SMARCA4 (p = 0.015), TERT (p = 0.0041), and IDH1 (p = 0.0041) were significantly exclusive to BM while the same variants remained undetected in the corresponding extracranial tumor tissues." (PMID 33578810, 2021). "Several relevant genes have been associated with a high tumour mutational burden (including ARID1A, RNF43, BRAF and KM2B in microsatellite instability (MSI) cancers) and may help select MSS tumours for immunotherapy." (PMID 34694371, 2021). "This is also seen in our cohort in which, in addition to the hyperprogression case, both non-hyperprogression treatment episodes with a 50% increase in volumetric tumor growth per month and a twofold increase in tumor growth experienced previous disease progression on a BRAF inhibitor." (PMID 32929554, 2021). "No patients in the enrolled cohort had a known BRAF or EGFR mutation or an ALK rearrangement in their primary tumor." (PMID 34642329, 2021). "Generally, BRAF and RAS mutations are thought to be mutually exclusive and are correlated with different clinical and histopathological presentations, though they can rarely be found together in separate clonal subpopulations of a given tumor." (PMID 35008286, 2021). "The BRAF V600E mutation has been found to not be associated with an incomplete response during follow-up, despite its correlation with older age and advanced tumor stage." (PMID 34070605, 2021). "CDX2 is absent in around 10% of CRC cancers, and CDX2-negative tumours are often associated with several adverse prognostic features, such as advanced stage, vascular invasion, poor differentiation, right-sided location, CIMP, and BRAF mutation." (PMID 34940086, 2021). "Initially, mutation detection in postoperative tumor tissue by using amplification-refractory mutation system polymerase chain reaction indicated wild-type RAS/BRAF without point mutations, insertion deletions, or fusion mutations." (PMID 34888240, 2021). "The primary aim of this study was to assess whether the addition of palbociclib could augment anti-tumor responses in combination with adoptive cell transfer and BRAF-MEKi." (PMID 34944961, 2021). "Tumours showing MSI or MLH1 loss should subsequently undergo BRAF mutation testing followed by MLH1 promoter methylation analysis in the absence of a BRAF mutation." (PMID 34944430, 2021).
tumor (continued). "Mutations in ARID1A, ARID2, BRAF, SMARCA4, TERT and IDH1 were significantly exclusive to intracranial metastases while the same variants remained undetected in the corresponding extracranial tumor tissues." (PMID 33578810, 2021). "Most importantly, the ROC AUC score of TMB was 0.780, which was the most reliable indicator in the survival prediction of the model compared with age (AUC = 0.658), gender (AUC = 0.421), AJCC-T (AUC = 0.668), N (AUC = 0.566), M (AUC = 0.611), tumor stage (AUC = 0.708), or BRAF status (AUC = 0.520)." (PMID 34248843, 2021). "Next, we performed a univariate analysis to evaluate the association among the EMT-TF expressions and several clinicopathological parameters, including age at the moment of diagnosis, gender, tumor histology, BRAF status, size (T), lymph node metastases (N), stage, and recurrences." (PMID 34575184, 2021). "Besides involvement in the tumor stage, miRNAs have been shown to modulate drug resistance mechanisms to immune check-point inhibitors and BRAF/MEK inhibitors." (PMID 33925387, 2021). "Intratumoural heterogeneity generated by both spatio-temporal factors (such as varying ATP levels within a tumour) and phenotypic factors (such as differences in BRAF amplification between cells) has been recognised to fuel drug resistance and complicate the design of treatment strategies." (PMID 34621046, 2021). "It was also unable to compare the prognostic performance of vascular-metabolic profiles to well-known pathological risk factors such as tumour regression score, circumferential resection margin, lymphovascular/perineural invasion, microsatellite instability, KRAS, NRAS, BRAF mutations." (PMID 33837843, 2021). "While anti-tumor effects of BRAF and MEK inhibitors could be enhanced with drugs targeting proteins involved in DNA repair, immunotherapy may draw benefit from directly interfering with the DNA integrity." (PMID 33800547, 2021). "However, even with these limitations in mind, it is important to note that tumor biopsies from patients under BRAF/MEK inhibitor therapy are rarely performed." (PMID 33275172, 2021). "Concerning the underlying mechanism for this specific AE, it has been demonstrated an increase in tumour-infiltrating lymphocytes in samples from patients after the beginning of BRAF inhibitor therapy, and the extent of infiltration correlates with tumour response." (PMID 32783159, 2021). "For NSCLC in particular, different studies have shown that TMB in the primary tumour tends to be higher in men than in women and is also positively correlated with tobacco consumption, KRAS, and BRAF mutated tumours, whereas the presence of ROS1 and ALK rearrangements is linked to lower TMB." (PMID 34683113, 2021). "Strong correlations between KRAS/BRAF-mt and tumour budding have been reported." (PMID 34940086, 2021). "Notably, IHC staining for CD8 T cells in the one BRAF KO tumor showed that even with this one sample, there was significant T-cell infiltration of the tumor." (PMID 33674596, 2021). "Furthermore, frequencies of BRAF and TERT promoter mutations in the tumor tissues were also found to be in line with previous studies." (PMID 33915745, 2021). "There are marked similarities between tumor invasion and trophoblast implantation, so our results may suggest that BRAF-mutant GBM may co-opt trophoblast-like properties to facilitate their growth and spread." (PMID 34625582, 2021). "Tumor progression is often observed after the termination of BRAF/MEK inhibitors." (PMID 34828788, 2021).
tumor (continued). "Some research indicates that BRAF inhibitors may enhance the efficacy of checkpoint inhibitors by regulating the tumor immune microenvironment, which may have an impact on our research conclusions." (PMID 34113648, 2021). "Patients receiving first-line systemic treatment with a BRAF mutation had a higher risk for shorter survival in multivariable analysis, although nonsignificant, which is reflected with an 8-month difference in the unadjusted median OS in patients with a BRAF mutant versus BRAF-wildtype tumour." (PMID 33046804, 2021). "In elderly HGSOC, mutations in the genes that are involved in the Ras and or PIK3CA signaling pathways were detected in nine samples (15%), including the genes KRAS and BRAF (each one in 1 tumor); PIK3CB and MTOR (each one in 2 tumors); and NF1 (in three different samples)." (PMID 34944094, 2021). "The drugs had little effect on tumours harbouring only BRAF V600E." (PMID 34359670, 2021). "Furthermore, an abundance of BRAF(V600E) ctDNA in treatment-naïve patients was related to tumor burden, with lower concentration reflecting longer OS and PFS compared to higher concentration (27.7 vs. 8.6 months and 9 vs. 3 months, respectively)." (PMID 34575876, 2021). "The BRAF gene regulates the growth of PTC tumour cells through TSHR." (PMID 34923978, 2021). "Additionally, overexpression of AIM2 significantly inhibits tumor growth and metastasis in BRAF-mutant CRC in vivo, which was further confirmed in BRAF-mutant CRC PDOs." (PMID 33842454, 2021). "Next, the BRAF V600E and BRAF WT assay was tested in patient tumor and plasma samples." (PMID 33799709, 2021). "Consequently, concordance in BRAF-V600E tumor status and metastases was observed only in 50% of patients: 10% for a positive status in the primary tumor and metastases and 40% for a negative status." (PMID 34319022, 2021). "Thus, our in vivo data largely reflects our in vitro findings and suggests that combination therapy is necessary to induce substantial tumor shrinkage in tumors harboring activating EGFR and BRAF mutations." (PMID 34921211, 2021). "Single-agent BRAF inhibition increased the presence of TAMs and Tregs in tumours." (PMID 34960140, 2021). "Further, combination with MEK1/2 and/or BRAF inhibitors may allow for reduction of radiotherapy dose while maintaining tumor control." (PMID 34604027, 2021). "As a particular focus was given to the expressional status of FRMD5 in BRAF-mutated PTCs, an analysis of FRMD5 activation status was performed on the BRAF-like molecular subtype of PTC and compared with other TC types and non-tumor (control) specimens." (PMID 34201607, 2021). "For patient P01 WES could be performed on the primary tumor and two metastatic samples, while insufficient tissue, unfortunately, precluded analysis of the BRAF-mutant metastasis." (PMID 34921211, 2021). "Thus, in such cases, it is required to resort to a surgical sampling of the metastasis for the BRAF status assessment, with further stress for the patient, or to the primitive tumor." (PMID 34207125, 2021). "The tall cell PTC variant, (BRAF V600E (+) in over 92%) has been described as a solid, hypoechogenic tumor with a spiculated/microlobulated margin, and a non-parallel orientation and with frequent nodal metastases." (PMID 34070605, 2021). "The concordance in the BRAF-V600E tumor status and LNMs was observed only in 50% of patients." (PMID 34319022, 2021).